BRCA1 (BRCA1 DNA repair associated)
Diseases named in the same sentence as BRCA1 in open-access papers (continued):
Sharing a sentence is not in itself a finding about the gene and the disease.
tumor (continued). "We also observed that patients with predicted biallelic inactivation of BRCA1 or BRCA2 had higher BRCA-like signature activity in both cfDNA and tumor biopsies (Wilcoxon rank-sum test, one-tailed, p < 0.01)." (PMID 29109393, 2017). "Much research has focused on the connected roles of BRCA1 and BRCA2 in HR, suggesting that impaired HR in their absence leads to genome instability that accelerates tumour development." (PMID 27452521, 2017). "BRCA1-DMS (BRCA1 deep mutational scanning) was generated from measured efficiencies of BRCA1 mutants in activities required for efficient homology-directed DNA repair (HDR) and tumour suppression." (PMID 28511696, 2017). "The current work features a new type of DNA damaging agent with enhanced potency against BRCA1/2 mutants and MGMT-proficient tumour cells." (PMID 28800752, 2017). "However, recent studies suggest that loss of Beclin-1 may be a passenger mutation, since loss of BRCA1 and Beclin-1 itself does not have an effect on tumor suppressor functions." (PMID 28753959, 2017). "BAP1 encodes a nuclear ubiquitin carboxyterminal hydrolase, which is a class of deubiquitinating enzymes, and contains binding domains for BRCA1 and BARD1 to form a tumor suppressor complex among other functions." (PMID 28302097, 2017). "Methylation levels ≥ 25% were only obtained for the promoters of APC in 44% (8/18), BRCA1 and CDKN2A in 11% (2/18) and ESR2 in 12% (2/17) of the tumor tissues and in addition for ESR2 in 6% (1/18) of the tumor-distant tissues." (PMID 28403857, 2017). "Sequencing of BRCA1 and BRCA2 using tumor‐derived DNA is hampered by the complexity of these genes, the low quality of the DNA derived from formalin‐fixed, paraffin‐embedded (FFPE) tumor samples and the low percentage of neoplastic cells in these samples." (PMID 27767231, 2017). "Methylation profiling of FBC was able to discriminate BRCA1, BRCA2 and two subsets of BRCAX tumours." (PMID 28893223, 2017). "In case of BRCA1 (r = 0.994, p < 0.001), exon 2 of CDKN2A (r = 0.651, p = 0.003) and ESR2 (r = 0.580, p = 0.015), methylation levels in tumor-adjacent tissues correlated with those in tumor-distant tissues." (PMID 28403857, 2017). "Furthermore alterations in such genes have been identified also in sporadic breast tumors with early age of onset, hormone receptors (ER/PgR) negativity and a high tumor grade, but in absence of germline BRCA1/2 mutations, which define a BRCA-like phenotype defined as “BRCAness”." (PMID 28055979, 2017). "For the mice injected with BRCA1-mutant SUM149 cells, RAD51 KD and PARP inhibition significantly inhibited tumor growth in the early stage." (PMID 28359295, 2017). "Methylation levels of the BRCA1 promoter strongly correlated with those of the CDKN2A promoter in tumors (r = 0.990, p < 0.001), tumor-adjacent tissues (r = 0.920, p < 0.001) and tumor-distant tissues (r = 0.963, p < 0.001)." (PMID 28403857, 2017). "However, we found that tumors associated with BRCA1 mutations demonstrate heterogeneity in protein expression, and thus bulk sequencing, promoter methylation and LOH analysis may mask sub-populations of tumor cells that vary in regards to BRCA1 locus-specific LOH." (PMID 28831036, 2017). "Thus, its downregulation in BRCA1/2 individuals could promote tumor development." (PMID 29108258, 2017). "Thus, not all BRCA1-mutated tumors may generate a BRCA1-like profile probably due to a different etiology or heterogeneity of the tumor." (PMID 27756336, 2016).
tumor (continued). "BRCA1 accumulation to DNA damage sites is a crucial step for BRCA1’s function in DNA damage repair, and BRCT domains of BRCA1 are important for the tumor suppressor function of BRCA1." (PMID 26778126, 2016). "The BRCA1 mutation found in the tumor with RD is a stop-gain mutation also reported in ClinVar as pathogenic, but due to lack of RNAseq data we could not assess the relative expression of mutant and WT BRCA1 transcripts." (PMID 27959926, 2016). "In this regard, about 15% of our samples showed a complete deletion of the BRCA1 or BRCA2 genes, suggesting that LOH represents the most common event in tumor cells." (PMID 27793035, 2016). "Genes and related networks implicated by both data sets involved both known and novel disease mechanisms and highlighted the different roles of BRCA1 and CREBBP in the two tumor types." (PMID 27788148, 2016). "Therefore, UBXN1 may facilitate tumor progression by negative regulation of BRCA1." (PMID 27754413, 2016). "PALB2 mediates interactions between BRCA1 and BRCA2 proteins, acts as a scaffold connecting numerous tumor suppressors, stimulates Polη-dependent DNA synthesis and RAD51 recombinase activity." (PMID 27434671, 2016). "DBC1 expression was significantly associated with advanced clinicopathological factors such as high tumor stage, latent distant metastasis, platinum-resistance, elevated serum levels of CA125, high histologic grade, and BRCA1 expression." (PMID 25823848, 2015). "The BRCA1 locus product, BRCA1-IRIS, shares 1,365 residues with the full-length product of this locus, the tumor suppressor, BRCA1." (PMID 25583261, 2015). "Analytical sensitivity for detection of germline copy number changes in BRCA1 and BRCA2 genes in normal, tumour and ascites samples—concordance between MLPA and results from the MLPA-seq." (PMID 26569395, 2015). "Maintenance of expressed BRCA1 protein interaction with BARD1 was quantified, as a marker of BRCA1 functionality, and the tumor expression profiles of 27 microRNAs were determined." (PMID 26490435, 2015). "Semi-quantitative scoring analysis showed that BRCA1-IRIS (P <0.0001) and survivin (P <0.0001) expression significantly increased concurrently with the increase in tumor aggressiveness." (PMID 25583261, 2015). "BRCA1 expression also differs by tumor microarray (BRCA1 elevated 2.16-fold, 4.38% FDR) along with alterations in the ATM/BRCA1 pathway using GSEA analysis." (PMID 25970777, 2015). "While the reduction of BRCA1 and RAD17 expression in sporadic cancers is well established, the molecular mechanisms by which their expression is downregulated in tumour cells are still unclear." (PMID 25650659, 2015). "We assessed the methylation status of BRCA1 promoter in the TNBC and GBM tumours for the two patients." (PMID 25880076, 2015). "We show that this method can detect BRCA1, BRCA2, ERBB2 and CCNE1 copy number changes in DNA extracted from snap-frozen and FFPE tumour tissue, with 100% sensitivity and >99.5% specificity." (PMID 26569395, 2015). "Under suboptimal cultivation conditions (no filter support or low oxygen with filter support), the down-regulation of BRCA1 and BLM (DDR) and up-regulation of HERPUD1 was common to slices from all three tumour xenograft models." (PMID 26647838, 2015). "Interruption of BRCA1 and BRCA2 expression or their function is also found to enhance radiosensitivity and the chemotherapeutic effectiveness of tumor cells." (PMID 25337721, 2014). "Linear correlations were observed between peripheral blood and tumor tissue expression levels for RRM1 (R2 = 0.045, P = 0.048) and BRCA1 (R2 = 0.021, P = 0.001)." (PMID 24591771, 2014).
tumor (continued). "Future studies of additional BRCA1 and BRCA2 carriers with detailed tumor pathology information on new and previously recruited mutation carriers are needed." (PMID 25919761, 2014). "However, the impact of BRCA1 on tumor cell metabolism remains unclear." (PMID 25010005, 2014). "The BRCA1 protein contains C-terminal tandem BRCT domains that are phosphoprotein binding motifs, which are important for the tumor-suppressor and DNA repair function of BRCA1." (PMID 24831086, 2014). "To evaluate the degree of FANCA-BRCA1 co-expression, we measured the correlation coefficient of FANCA and BRCA1 expression in the Rb-tumor cohort." (PMID 25161863, 2014). "In the present study, BRCA1 and TS mRNA levels in plasma were correlated with levels in paired FFPE tumor tissue." (PMID 25496700, 2014). "Pyruvate and lactate, the final glycolysis products, were both decreased by BRCA1 transfection (p = 0.061 for lactate and p = 0.014 for pyruvate), while ATP levels in SUM1315-BRCA1 tumor cells were increased." (PMID 25010005, 2014). "DNA was isolated from tumor samples as well as normal tissues from 77 TNBC patients and the genetic sequence of the BRCA1/2 exons and flanking regions determined." (PMID 25051360, 2014). "We also found higher expression of the NFκB-signalling TFs in BRCA1 tumours - the complex NFκB1-NFκB2-REL-RELA-RELB composed entirely of NFκB TFs, showed a higher correlation in BRCA1 tumours than BRCA2 tumours." (PMID 25521701, 2014). "This indicates that 66.7% (10/15) of patients harbored methylated BRCA1 promoter in both WBC and tumors, which reveals strong correlation between the presences of methylated BRCA1 promoter in WBC and matched tumor tissues." (PMID 25403427, 2014). "We analyzed the protein expression of MRE11, MDC1, ATM, ATR and BRCA1 by immunohistochemistry (IHC) in 97 SOC samples, and correlated with clinical parameters including age, tumor grades, clinical stage, status of menstruation and chemotherapy." (PMID 24752797, 2014). "The linear correlations of the relative expression of mRNA were observed between peripheral blood and tumor tissue expression levels for RRM1 and BRCA1." (PMID 24591771, 2014). "Among these, BRCA1 and BRCA2 tumours are phenotypically most different and we consider these two for our analysis here; our dataset contains 19 BRCA1 and 30 BRCA2 expression samples (GEO accession GSE19177)." (PMID 25521701, 2014). "Irinotecan treatment results in the accumulation of DNA strand breaks in tumor cells, and APTX, BRCA1 and ERCC1 have been shown to have important roles in the repair of DNA single- and double-strand breaks." (PMID 23517622, 2013). "However, the contribution of these functions of BRCA1 to tumor suppression is unknown." (PMID 23802008, 2013). "Here, we will review BRCA1 functions in the DNA damage response (DDR), which are likely to contribute to tumor suppression." (PMID 23802008, 2013). "Multiple studies have shown that aCGH classifiers can be built to distinguish BRCA1 and BRCA2 tumours from sporadic tumours and each other." (PMID 23383274, 2013). "In our study group, 37.5%, 61.60%, 58.92% and 20.53% of the ESCC tumours had p16, DAPK, GSTP1 and BRCA1 promoter methylation respectively, which was significantly higher than adjacent normal tissues." (PMID 23596512, 2013).
tumor (continued). "In conclusion, the present study showed aberrant tumor-specific methylation alterations for APC, BIN1, BMP6, BRCA1, CST6, ESR-b, GSTP1, P14, P16, P21, PTEN and TIMP3 in the studied cohort." (PMID 22695536, 2012). "Together, these data suggest that part of BRCA1-IRIS oncogenic function lies in its ability to promote formation of apoptosis resistance and thus aggressive tumor cells." (PMID 22511931, 2012). "The peroxisome proliferator-activated receptorγ (PPARγ) is a key regulator of metabolism, proliferation, inflammation and differentiation, and upregulates tumor suppressor genes, such as PTEN, BRCA1 and PPARγ itself." (PMID 22538444, 2012). "Of the 110 TNBC patients included in this study and for whom germline status of BRCA1 and BRCA2 has been characterized (see earlier), 34 had adequate invasive tumor tissue for evaluation." (PMID 23116406, 2012). "BRCA1-IRIS- and RasV12-induced subcutaneous tumors were embedded in paraffin, sectioned at 4 μm in the middle of each tumor, stained with hematoxylin and eosin (H&E) and blindly analyzed by 2 pathologists." (PMID 22511931, 2012). "Relationships between BRCA1-IRIS level and marker expression and tumor characteristics in Her2+ and TN/BL breast cancer tumor samples." (PMID 22511931, 2012). "Hierarchical clustering showed significant hypermethylation patterns for serum and tumor tissue compared with normal tissue for seven genes (APC, BIN1, BMP6, BRCA1, CST6, P16 and TIMP3)." (PMID 21283676, 2011). "In our study group, 4.0% of the patients displayed methylation of BRCA1 and APC in both tumor and the corresponding PB DNA." (PMID 22129206, 2011). "Two-way hierarchical clustering in serum and tumor tissue showed significant hypermethylation patterns of seven genes (APC, BIN1, BMP6, BRCA1, CST6, P16 and TIMP3) compared with normal tissue." (PMID 21283676, 2011). "Three BRCA1-likeaCGH tumours were classified as Sporadic-like by MLPA and two Sporadic-likeaCGH tumours were typed as BRCA1-like." (PMID 22032731, 2011). "Moreover, as mutations in genes other than BRCA1 and BRCA2 affect HR, it is entirely possible that some of the samples classified as “non-BRCA” could also have a similar HR deficiency to BRCA1/2 mutant tumours." (PMID 21750719, 2011). "The eight genes displaying variable DNA methylation patterns in a significant number of tumours (ABCB1, BRCA1, CDKN2A, FOXC1, GSTP1, IGF2, PPP2R2B and PTEN) within the discovery cohort were tested for association with survival by a logrank test." (PMID 20338046, 2010). "It would be extremely interesting to identify the ubiquitin ligase mediating BRCA1/BARD1 downregulation, as well as to determine how defects in this pathway affect tumor suppressor function." (PMID 21103343, 2010). "BRIT1 protein (also known as MCPH1) contains 3 BRCT domains which are conserved in BRCA1, BRCA2, and other important molecules involved in DNA damage signaling, DNA repair, and tumor suppression." (PMID 20107607, 2010). "Therefore no support was found for the hypothesis of a predisposing tumour suppressor gene similar to the BRCA1 and BRCA2 genes." (PMID 20637093, 2010). "Furthermore, hypoxia in basal type/BRCA1 tumours may lead to the preferential degradation of PHD3." (PMID 19724277, 2009). "a common feature of tumor microenvironments, represses expression of tumor suppressor genes (e.g., E-CAD, BRCA1, MLH1, and RUNX) frequently silenced in cancer." (PMID 19279688, 2009).
tumor (continued). "The combined analysis of genomic alterations and tumour phenotypes, presented here, show that BRCA1- and BRCA2-related tumours develop largely through different genetic pathways in terms of the regions altered, while also displaying distinct phenotypes." (PMID 19589159, 2009). "The results suggest that BRCA1- and BRCA2-related tumours develop largely through distinct genetic pathways in terms of the regions altered while also displaying distinct phenotypes." (PMID 19589159, 2009). "In contrast to MLH1, BRCA1 and BRCA2 expression demonstrated greater variability between paired primary and recurrent neoplasms." (PMID 19602291, 2009). "However, the BRCA1-2 mutation rates were significantly higher in the subsets of patients with a more undifferentiated primary carcinoma (tumor grading 3–4, P < 0.001) and lack of expression of estrogen receptor (ER-, P = 0.002) or progesterone receptor (PR-, P = 0.007)." (PMID 19619314, 2009). "Classical tumour suppressor genes and genes involved in chemosensitivity, such as hMLH1, p16, p15, Rb, VHL, E-cadherin, GSTP1, and BRCA1, or the DNA repair gene MGMT, undergo epigenetic inactivation by hypermethylation of their regulatory regions." (PMID 19144202, 2009). "Although BRCA1- and BRCA2-related tumours develop through alterations affecting different regions in their genomes they showed similarities in their genomic architecture patterns with large segments of deletions being prominent." (PMID 19589159, 2009). "DNA from the first tumour was available for analysis and both MethyLight and MS-HRM assays indicated that BRCA1 methylation was present." (PMID 18269736, 2008). "Tumours from familial non-BRCA1/BRCA2 patients were similar to sporadic ones, although they were of lower stage and CK-14 was expressed more often than among sporadic tumours." (PMID 18275599, 2008). "The tumor suppressor network in which p73 appears to be a participant involves E2F1, JunB, INK4a/p16, ARF/p19, p57kip2 and BRCA1." (PMID 17407586, 2007). "Concomitant losses of the BRCA1 region, which is located at the marker D17S855 together with the BRCA2 region were significantly related to the histological grade of the tumor." (PMID 17915011, 2007). "The tumor suppressor pathway in which p73 appears to be a participant involves E2F1, JunB, p16, p19, p57kip2 and BRCA1." (PMID 17407586, 2007). "In contrast to this, c-Myc was found to be amplified in 23% (3/13) of BRCA1 and 67% (4/6) BRCA2 tumours." (PMID 16595007, 2006). "BRCA2 tumours expressed cyclin D1 and D3, cyclin D kinase (CDK) 4 and the CDK inhibitors, p16, p21, and p27, which were all downregulated in BRCA1." (PMID 16595007, 2006). "BRCA1 and BRCA2 tumours have also recently been subjected to TMA analysis in which 37 biomarkers were used to define hormone receptor, cell cycle, apoptosis and basal cell status." (PMID 16595007, 2006). "Furthermore, tumours from the older BRCA2 carriers exhibited distinctly different characteristics from the younger ones or from BRCA1 carrier tumours and mutation-negative ones, suggesting a strong impact of the germline mutation on tumour development among the older patients." (PMID 15987451, 2005). "The erbB2 results were very similar in the three groups of familial cases, with 18.6%, 15.1% and 17.4% of the BRCA1, BRCA2 and non-BRCA1/2 tumours, respectively, expressing the erbB2 antigen." (PMID 15642173, 2005). "Of course, a potential confounding issue was the differential distribution of ER between the BRCA1 and BRCA2 tumours." (PMID 15714204, 2005).